FOXO1 (forkhead box O1)
Diseases named in the same sentence as FOXO1 in open-access papers (continued):
Sharing a sentence is not in itself a finding about the gene and the disease.
metastatic disease (14 papers, 2012 to 2025). "Although the prognostic role of FOXO1 fusion status is widely accepted in localized disease, it is still controversial in metastatic disease." (PMID 39781573, 2025). "Six characteristics differed by race/ethnicity: age, histology, IRS group, invasiveness, metastatic disease, and FOXO1 fusion partner." (PMID 37081771, 2023). "We found six genes such as SPP1, VEGFA, POSTN, RUNX2, CD44, and FOXO1 that were consistently overexpressed in patients with bone metastasis compared to non-metastatic tumors." (PMID 36424413, 2022). "Pairwise analysis between Non‐Hispanic Black versus Non‐Hispanic White patients and Hispanic versus Non‐Hispanic White patients for age group, RMS histology, Intergroup Rhabdomyosarcoma Study (IRS) group, tumor invasiveness, metastatic disease, and FOXO1 fusion partner (PAX3 or PAX7)." (PMID 37081771, 2023). "Interestingly, while fusion subtype does not affect survival of patients presenting without clinically overt distal metastases, patients presenting with PAX3/FOXO1 metastatic disease appear to have worse outcomes than those with PAX7/FOXO1 metastatic disease." (PMID 32697014, 2020). "For patients with metastatic disease, FOXO1 fusion status was the strongest prognostic variable." (PMID 31456361, 2019). "Similarly, patients with a high MG5 score had a very poor outcome similar to the FOXO1 fusion‐positive patients, and could be targeted for novel approaches used for patients with metastatic disease." (PMID 31456361, 2019). "In metastatic disease, patients with PAX7::FOXO1 aRMS were significantly younger compared to PAX3::FOXO1 positive group (68% vs. 33% of patients ≤10 years of age), all other factors were similarly distributed." (PMID 39781573, 2025). "Multivariate analysis in patients with metastatic tumors, identified PAX3::FOXO1 fusion as an independent adverse prognostic factor for EFS and OS, B/BM involvement for EFS only." (PMID 39781573, 2025). "Multivariate analysis identified PAX3::FOXO1 fusion as an independent adverse prognostic factor for EFS in patients with localized disease and for EFS and OS in patients with metastatic disease, B/BM metastases for EFS." (PMID 39781573, 2025). "Many studies have identified FOXO1 fusion status as a prognostic factor in RMS and have also reported on the additional impact of clinical factors, but most have analyzed localized and metastatic tumors together and been conducted with convenience cohorts." (PMID 39781573, 2025). "By pairwise analysis of NHB and NHW patients, histology, IRS group, the presence of metastatic disease, and FOXO1 fusion partner were not significantly different." (PMID 37081771, 2023). "The mRNA (messenger ribonucleic acid) expression levels of SIRT1, FoxO1 and FoxO3a were significantly decreased in 4TLM metastatic tumors compared to 67NR non-metastatic tumors, whereas the FoxO4 signal was significantly increased in metastatic tumors (p ˂ 0.05)." (PMID 36142156, 2022). "FOXO1 status (positive vs negative) was significant in the second split both for localized (EFS 52% vs 78%; OS 65% vs 88%) and metastatic disease (EFS 6% vs 46%; OS 19% vs 58%)." (PMID 31456361, 2019). "Among patients with metastatic disease, patients aged >10 years, with FP tumors, PAX3::FOXO1 fusion type and B/BM involvement, had significantly worse EFS and OS compared to patients aged ≤10 years, without B/BM involvement, FN tumors, or with PAX7::FOXO1 fusion type." (PMID 39781573, 2025).
neuroblastoma (14 papers, 2019 to 2025). Neuroblastoma (NB) is the most common solid, extracranial childhood tumor. "This indicated that the AKT signaling pathway was involved in the transportation of FOXO1 and RB1 by XPO1.Our research confirmed that verdinexor inhibited neuroblastoma proliferation and induced apoptosis through nuclear accumulation of FOXO1 and RB1." (PMID 34384466, 2021). "We show that vorinostat and panobinostat induce autophagy, transcriptionally upregulate autophagy related genes in neuroblastoma cells and induce nuclear translocation of the autophagy transcription factors FOXO1 and FOXO3a." (PMID 33923163, 2021). "Verdinexor, the specific inhibitor of XPO1, suppressed the neuroblastoma cell growth and induced cell apoptosis by FOXO1 and RB1 nuclear accumulation through inhibition of the PI3K/AKT pathway." (PMID 34384466, 2021). "Inhibition of XPO1 by the specific inhibitor verdinexor suppressed neuroblastoma cell growth and induced cell apoptosis through FOXO1 and RB1 nuclear accumulation by inhibiting the PI3K/AKT pathway." (PMID 34384466, 2021). "In our study, treatment of neuroblastoma cells with broad-spectrum HDACi vorinostat and panobinostat promoted autophagy via activation of FOXO1 and FOXO3a." (PMID 33923163, 2021). "Moreover, a previous study illustrated that FoxO1 induces the proapoptotic proteins Noxa and Bim, which gives rise to cytochrome c release in neuroblastoma." (PMID 31905813, 2019). "Importantly, FoxO1 induces autophagy in various cells and diseases including neuroblastoma." (PMID 40692791, 2025). "Among neurologic tumors, in neuroblastoma (NB), lncRNA MEG3 functions as an anti-tumor agent, and overexpressing MEG3 in NB cells decreased epithelial-mesenchymal transition invasion and metastasis via mTOR signaling and inhibited FOXO1-mediated autophagy." (PMID 38933333, 2024). "In neuroblastoma (NB), miR-223 can bind to the 3′UTR of FOXO1, resulting in decreased expression of FOXO1, thus increasing the malignant ability of NB cells." (PMID 37465640, 2023).
acute myeloid leukemia (13 papers, 2012 to 2025). Acute myeloid leukemia (AML) is a group of neoplasms arising from precursor cells committed to the myeloid cell-line differentiation. "The polycomb repressive complex 1.1 has been reported to participate in establishing a closed chromatin conformation at the Foxo1 locus in acute myeloid leukemia blasts." (PMID 36439112, 2022). "In acute myeloid leukemia FOXO1/3/4 promote leukemic growth and maintenance by inhibiting myeloid maturation and apoptosis." (PMID 22916022, 2012). "Thus, in APL, a member of FOXOs family acts as tumor suppressor gene differently from the previously reported role of FOXO1 in RUNX1-RUNX1T1 acute myeloid leukemia." (PMID 31234353, 2019). "It has been reported that FOXO1 can play a role in the development of acute myeloid leukemia (AML)." (PMID 31874600, 2019). "The first steps towards testing FoxO1 inhibition in cancer were conducted in acute myeloid leukemia (AML)." (PMID 39533662, 2025). "Foxo1 was required for canonical WNT gene expression in osteoblasts and a murine acute myeloid leukemia (AML) model induced by activated beta‐catenin." (PMID 37584250, 2023). "Our work demonstrates that FOXO1 promotes canonical WNT gene expression in examined BBC and GBM cells, similar to results found in Drosophila melanogaster, T‐cell development, and murine acute myeloid leukemia models." (PMID 37584250, 2023). "It has been reported that conditional deletion of FoxO1, FoxO3 and FoxO4 simultaneously results in the development of hemangiomas and thymic lymphomas, and IκB kinase represses FoxO3a activity to promote human breast tumorigenesis and acute myeloid leukemia (AML)." (PMID 26474173, 2015).
hyperlipidemia (13 papers, 2014 to 2025). "The hepatic suppression of FOXO1 and FOXO3 causes hypoglycemia and hyperlipidemia in FOXO1 and FOXO3 knockout mice; moreover, the expression of hepatic FOXOs affects the reduction of gluconeogenic gene expression and insulin resistance." (PMID 35256743, 2022). "Decreased forkhead box O1 (FoxO1) activity induces hyperlipidemia and increased PPARγ, leading to hyperlipidemia in association with endoplasmic reticulum (ER) stress." (PMID 31235676, 2019). "Hyperlipidemia and CKD, which were observed in the SDT fatty rats and were attenuated by the exercise training, were reported to increase muscle FOXO1 expression." (PMID 37016292, 2023). "Furthermore, the mRNA expression of SIRT1 and FOXO1 slightly increased, while FAS was subsequently decreased in the perirenal adipose tissue, which demonstrated a reduction in fatty acid synthesis and therefore reduced the development of hyperlipidemia." (PMID 37835191, 2023).
Hypertension (13 papers, 2014 to 2025). The presence of chronic increased pressure in the systemic arterial system. "Their transcription levels correlate with the transcription levels of several genes encoding transcription factors associated with the response to oxidative stress, including transcription factors associated with hypertension (Arnt, Atf4, Ddit3, Foxo1)." (PMID 39594444, 2024). "While some evidence from animal studies have found FoxO1 to be protective to the heart, others have reported that increasing FoxO1 expression increase angiotensinogen and angiotensin II levels, which are important in the pathogenesis of hypertension." (PMID 37089429, 2023). "It is possible that chronic elevation of TMAO has the potential to chronically activate the PERK pathway and FoxO1 expression, and possibly contribute to the development of hypertension." (PMID 37089429, 2023). "Forkbox O1(FoxO1) signaling protects cells against oxidative stress and may be a useful target for treating oxidative stress-induced hypertension." (PMID 26673167, 2015). "Additional adjustment for traditional cardiovascular risk factors and markers (BMI, smoking status, hypertension, total cholesterol, HDL-cholesterol, hsCRP) even improved the strength of this association (p = 0.0037 for SIRT1 and p = 0.0002 for both SNPs at FOXO1)." (PMID 25273948, 2014). "Many reports showed that CETP, LIPC and LIPG were associated with HDL and LDL and that MTHRR had known main effects for LDL and blood pressure, NR1I3 for lipid metabolism, PLTP for LDL, FOXO1 for LDL and hypertension, SMAD9 for hypertension, and CSMD1 for SBP." (PMID 27104857, 2016).
Hypoglycemia (13 papers, 2012 to 2024). A decreased concentration of glucose in the blood. "Liver-specific FoxO1 knockout mice displayed fasting hypoglycemia associated with reduced expression of gluconeogenic genes." (PMID 29614722, 2018). "Furthermore, in vivo experiments showed that Akt phosphorylation resistant FOXO1 3A mutant is sufficient to rescue the hypoglycemia caused by MKP-3 knock down in the liver of lean mice (from 141±6.78 to 209±14.64 mg/dL)." (PMID 22848439, 2012). "In an animal study, estrogen (estradiol or E2) acts via the estrogen receptor α-phosphoinositide 3-kinase (PI3K)-Akt-Foxo1 signaling resulting in increased glucose uptake leading to females tend to develop hypoglycemia due to the influence of estrogen." (PMID 36371171, 2022). "For example, SIRT1 promotes FOXO1 deacetylation and PPARs activation to stimulate gluconeogenesis and fatty acid oxidation, thus inhibiting lipogenesis in organisms under hypoglycemia stress." (PMID 32397268, 2020). "Modulation of FOXO1 with fetal exposure to nutrient restriction and hypoglycemia has been found in fetal sheep." (PMID 25524279, 2014). "Hepatic FoxO1/3/4 knockout mice have been previously shown to develop hypoglycemia at postnatal and adult ages." (PMID 24015318, 2013). "Furthermore, the effect of the Akt phosphorylation resistant FOXO1 mutant on rescuing the hypoglycemia in mice with reduced hepatic MKP-3 expression was also studied." (PMID 22848439, 2012). "FOXO1 is involved also in the regulation of hepatic synthesis of glucose in response to hormonal and nutrient stimuli by promoting its production to prevent life‐threatening hypoglycemia during prolonged starvation (Matsumoto, Pocai, Rossetti, Depinho, & Accili, 2007)." (PMID 33664777, 2021). "Through effects on insulin-secreting β cells, EPE increases the release of endogenous insulin via insulin-p-Akt-p-FoxO1 and/or via hepatic p-AMPK to suppress the hepatic PEPCK pathway and improve muscle membrane GLUT4 protein levels, thereby producing hypoglycemia." (PMID 37850072, 2023).
keratoconus (13 papers, 2017 to 2025). A degenerative, structural disorder of the eye, characterized by a cone-shaped protrusion of the cornea. "FOXO1 is a well-established susceptibility gene for keratoconus, while the association of SMAD3 with keratoconus susceptibility remains unclear." (PMID 30127857, 2018). "Indeed, the contribution of variant near FOXO1 to keratoconus susceptibility has already been identified by Lu’s study." (PMID 30127857, 2018). "We identified 8 SNPs in 6 genes/loci that were associated with keratoconus, i.e., FOXO1 rs2721051, FNDC3B rs4894535 and BANP-ZNF469 rs9938149 for the overall combined cohorts, and RXRA-COL5A1 rs1536482, IMMP2L rs757219 and rs214884, and COL4A4 rs2229813 and rs2228557 for Whites." (PMID 28676647, 2017). "As for genetic factors, alterations in Lysyl oxidase (LOX), Collagen Type V Alpha 1 Chain (COL5A1), and Forkhead box protein O1 (FOXO1) gene have been correlated to keratoconus pathogenesis." (PMID 35054085, 2022). "We found that rs1536482 near the COL5A1 gene, rs2721051 near the FOXO1 gene, and rs1324183 near the MPDZ gene were significantly associated with keratoconus in a Russian cohort." (PMID 34625056, 2021). "The minor allele distribution was significantly different (p-value < 0.05) between the keratoconus and main control groups for all three SNPs: rs1536482 near the COL5A1 gene, rs2721051 near the FOXO1 gene, and the rs1324183 minor allele near the MPDZ gene." (PMID 34625056, 2021). "For example, FOXO1, RXRA and FNDC3B are the 3 genes that showed genome-wide significant association with keratoconus." (PMID 28676647, 2017). "The purpose of this study was to validate whether three reported keratoconus-associated SNPs (rs1536482 near the COL5A1 gene, rs2721051 near the FOXO1 gene, rs1324183 near the MPDZ gene) are also actual for a Russian cohort of patients." (PMID 34625056, 2021). "Of the 36 CCT SNPs tested for association with disease risk in the keratoconus studies, three were significant and with the expected direction of effect (rs66720556 between MPDZ-NFIB, rs3132303 between RXRA-COL5A1, and rs2755238 close to FOXO1)." (PMID 29760442, 2018). "In conclusion, we have prioritized 8 SNPs in 6 genes/loci as significant genetic markers for keratoconus in Whites, including FOXO1 rs2721051, RXRA-COL5A1 rs1536482, FNDC3B rs4894535, IMMP2L rs757219 and rs214884, and BANP-ZNF469 rs9938149, and COL4A4 rs2229813 and rs2228557." (PMID 28676647, 2017). "This study aimed to investigate the replication of three SNPs (rs1536482 near the COL5A1 gene, rs2721051 near the FOXO1 gene, rs1324183 near the MPDZ gene) with keratoconus in the largest sample of patients from Russia." (PMID 34625056, 2021). "Further studies of the roles of SMAD3, FOXO1, and TGF-β signalling in keratoconus development are needed." (PMID 32737415, 2020). "Overall, we found a significant negative correlation of effect sizes across CCT and keratoconus (r = −0.62, P = 5.30 × 10−5), this correlation was largely unchanged if the known SNPs in ZNF469, FOXO1, COL5A1 and MPDZ/NFIB were removed from the analysis (r = −0.61, P = 2.04 × 10−4)." (PMID 29760442, 2018).
myocardial ischemia (13 papers, 2014 to 2025). A disorder of cardiac function caused by insufficient blood flow to the muscle tissue of the heart. "The Hippo pathway exacerbates myocardial ischemia/reperfusion injury by impeding YAP–Forkhead box protein O1 (FoxO1) function." (PMID 40066231, 2025). "Myocardial ischemia/reperfusion injury is larger in cardiac-specific FoxO1 knockout mice than in control mice." (PMID 39060225, 2024). "We further conducted ChIP sequencing analyses to evaluate the effect of C/EBP-β phosphorylation at Thr250 (mice) upon the ability of C/EBP-β and FoxO1 to bind to the promoter regions of the Cat and Mnsod genes during myocardial ischemia in vivo." (PMID 39060225, 2024). "During cardiac ischemia, FoxO1 is not only present, but also persists throughout the process of cardiac ischemia." (PMID 35371601, 2022). "RSV increased phosphorylation of FOXO1 through phosphorylation of AMPK and SIRT1, thereby reducing ROS and apoptosis level to alleviate myocardial ischemia–reperfusion injury." (PMID 35791579, 2022). "We then evaluated the role of Mst1, FoxO1, and C/EBP-β during 4 h of myocardial ischemia." (PMID 39060225, 2024).
nasopharyngeal carcinoma (13 papers, 2016 to 2025). A carcinoma arising from the nasopharyngeal epithelium. "A previous study had demonstrated that the overexpression of FOXO1 can significantly increase the expression levels of many target miRNAs (e.g. miR-125b, miR-99, miR-101, miR-let-7c, miR-675, miR-199a) to suppress nasopharyngeal carcinoma cell proliferation." (PMID 34307154, 2021). "In a newly published article by Li and colleagues, the role of FOXO1 in sensitizing nasopharyngeal carcinoma (NPC) cells to CP therapy was investigated mechanistically." (PMID 32503307, 2020). "A role for FoxO1 in mediating chemosensitivity of nasopharyngeal carcinoma has been demonstrated in a study reporting that miR-3188 regulates proliferation and chemosensitivity of this tumor type." (PMID 30646603, 2019). "Both in vitro and in vivo experiments have suggested that CB can improve the sensitivity of FOXO1-overexpressing nasopharyngeal carcinoma cells to cisplatin and promote their apoptosis, indicating that CB is a potential drug to fight against nasopharyngeal carcinoma." (PMID 36237327, 2022). "In this study, we present novel molecular mechanisms by which FOXO1 functions as a tumor suppressor to prevent the pathogenesis of nasopharyngeal carcinoma (NPC)." (PMID 31754475, 2019). "In fact, activated Akt correlates with phospho-FoxO1 and with phosphorylation of EGF receptor in nasopharyngeal carcinoma." (PMID 30646603, 2019). "Based on these findings, the FoxO1-miR-148a-5p-CREB1 axis is involved in STAT3-mediated regulation of SRGN and the promotion of nasopharyngeal cancer growth and metastasis, thereby confirming the role of STAT3 in the proliferation, invasion, and anti-apoptotic effects of NPC cells." (PMID 36313702, 2022).